MSX1 (msh homeobox 1)
Description:
Acts as a transcriptional repressor (By similarity). Capable of transcription autoinactivation (By similarity). Binds to the consensus sequence 5'-C/GTAAT-3' in downstream activin regulatory elements (DARE) in the gene promoter, thereby repressing the transcription of CGA/alpha-GSU and GNRHR (By similarity). Represses transcription of myoblast differentiation factors (By similarity). Binds to core enhancer regions in target gene promoters of myoblast differentiation factors with binding specificity facilitated by interaction with PIAS1 (By similarity). Regulates, in a stage-specific manner, a developmental program of gene expression in the fetal tooth bud that controls odontoblast differentiation and proliferation of dental mesenchymal cells (By similarity). At the bud stage, required for mesenchymal molar tooth bud development via facilitating reciprocal signaling between dental epithelial and mesenchymal cells (By similarity). May also regulate expression of Wnt antagonists such as DKK2 and SFPR2 in the developing tooth mesenchyme (By similarity). Required for BMP4 expression in dental mesenchyme cells (By similarity). Also, in response to BMP4, required for BMP4 expression in neighboring dental epithelial cells (By similarity). Required for maximal FGF4-induced expression of SDC1 in dental mesenchyme cells (By similarity). Also in response to SDC1, required for SDC1 expression in neighboring dental epithelial cells (By similarity). At the early bell stage, acts to drive proliferation of dental mesenchyme cells, however during the late bell stage acts as an homeostatic regulator of the cell cycle (By similarity). Regulates proliferation and inhibits premature mesenchymal odontogenesis during the bell stage via inhibition of the Wnt signaling component CTNNB1 and subsequent repression of the odontoblast differentiation factors BMP2, BMP4, LEF1, ALPL and BGLAP/OCN (By similarity). Additionally, required for correct development and fusion of the palatal shelves and embryonic mandibular formation (By similarity). Plays a role in embryonic bone formation of the middle ear, skull and nasal bones (By similarity). Required for correct formation and thickness of the nail plate (By similarity). May play a role in limb-pattern formation (By similarity).
Synonyms: HOX7; HYD1; OFC5; ECTD3; STHAG1
Tractability: PROTAC: UniProt records ubiquitination sites on it; ubiquitination databases record sites on it.
Gene: Protein-coding gene on chromosome 4 (4,859,665 to 4,863,936, forward strand). Ensembl gene ENSG00000163132.
Subcellular location: Nucleus
Subcellular location (Human Protein Atlas): Nucleoplasm
Pathways (Reactome):
Developmental Biology: Specification of the neural plate border
Gene Ontology:
Molecular function: protein binding; sequence-specific double-stranded DNA binding; DNA-binding transcription factor activity, RNA polymerase II-specific; RNA polymerase II transcription regulatory region sequence-specific DNA binding; transcription cis-regulatory region binding; cis-regulatory region sequence-specific DNA binding; DNA binding; DNA-binding transcription activator activity, RNA polymerase II-specific; DNA-binding transcription repressor activity, RNA polymerase II-specific; sequence-specific DNA binding
Biological process: cell morphogenesis; embryonic nail plate morphogenesis; face morphogenesis; negative regulation of cell growth; odontogenesis of dentin-containing tooth; protein localization to nucleus; protein stabilization; cardiac conduction system development; embryonic morphogenesis; inner ear development; negative regulation of gene expression; negative regulation of odontoblast differentiation; nose development; positive regulation of cell cycle; positive regulation of odontogenesis; regulation of odontogenesis; regulation of transcription by RNA polymerase II; roof of mouth development; animal organ morphogenesis; epithelial to mesenchymal transition; mesenchymal cell proliferation; negative regulation of transcription by RNA polymerase II; odontogenesis; and 2 more
Cellular component: nucleoplasm; nucleus; chromatin; nuclear periphery; transcription regulator complex
Genetic constraint (gnomAD): Loss-of-function variants: 11 observed, 14.11 expected, observed/expected ratio (o/e) 0.78, 90% interval 0.49 to 1.29. The synonymous counts are far from expectation, so gnomAD's model fits this gene poorly and the ratio says little. Missense variants: 477 observed, 397.84 expected, observed/expected ratio (o/e) 1.2, 90% interval 1.11 to 1.29. Synonymous variants: 253 observed, 194.67 expected, observed/expected ratio (o/e) 1.3, 90% interval 1.17 to 1.44.
Gene-disease validity (ClinGen):
ClinGen rates the evidence that MSX1 causes each of these diseases.
tooth agenesis, selective, 1 (autosomal dominant): Definitive.
tooth and nail syndrome (autosomal dominant): Disputed. Hypodontia-nail dysplasia syndrome is a form of ectodermal dysplasia.
Homologues: Orthologues: chimpanzee MSX1 (100% identical), macaque MSX1 (99% identical), dog MSX1 (97% identical), pig MSX1 (95% identical), guinea pig MSX1 (94% identical), rat Msx1 (94% identical), mouse Msx1 (94% identical), tropical clawed frog msx1 (65% identical), Drosophila melanogaster Dr (36% identical), Caenorhabditis elegans vab-15 (30% identical). Paralogues in human: MSX2 (51% identical).
Diseases named in the same sentence as MSX1 in open-access papers:
MSX1 is named in the same sentence as 124 diseases in open-access papers, as found by Europe PMC text mining. Sharing a sentence is not in itself a finding about the gene and the disease. The quoted sentences say what the papers report.
tooth agenesis (74 papers, 2009 to 2026). A tooth disease characterized by failure to develop one or more missing teeth. "Numerous case–control studies have reported the correlation between PAX9 rs2073247, PAX9 rs2073244, and MSX1 rs12532 gene polymorphisms and tooth agenesis." (PMID 40226363, 2025). "Tooth agenesis is typically caused by genetic mutations in MSX1, PAX9, and AXIN2 that affect tooth development." (PMID 40136761, 2025). "In this study, we investigated the use of machine learning to predict hypodontia risk based on selected SNPs in the MSX1, PAX9, and AXIN2 genes." (PMID 39183201, 2024). "We did not conduct functional experiments, so we cannot elucidate the specific mechanisms by which MSX1 gene variants lead to congenital tooth agenesis." (PMID 39767847, 2024). "In humans, MSX1 variations are associated with dental anomalies like tooth agenesis and orofacial clefting, as well as other conditions like nail dysplasia." (PMID 38523193, 2024). "MSX1 was the first gene discovered to cause non-syndromic tooth agenesis and has remained a focal point of research." (PMID 39767847, 2024). "On average, patients with non-syndromic tooth agenesis associated with MSX1 had an average of 8.96 missing teeth." (PMID 39767847, 2024). "This study has drawn a pattern diagram of congenital tooth agenesis caused by MSX1, which helps readers understand this phenotype more intuitively." (PMID 39767847, 2024). "Two main types of MSX1 gene variants are associated with non-syndromic tooth agenesis: missense variants and frameshift variants." (PMID 39767847, 2024). "Based on the frequency of tooth agenesis, we constructed a pattern diagram related to the MSX1 gene variant and non-syndromic tooth agenesis." (PMID 39767847, 2024). "The MSX1 gene, essential for tooth development, has been associated with non-syndromic tooth agenesis." (PMID 39767847, 2024). "We compiled data from a total of 108 patients with non-syndromic tooth agenesis caused by MSX1 variants." (PMID 39767847, 2024). "This study compiles cases of non-syndromic tooth agenesis attributed to MSX1 variants reported in previous research." (PMID 39767847, 2024). "The rs8670 variant in the MSX1 gene was found to potentially correlate with non-syndromic hypodontia in the upper lateral incisors, suggesting an impact on mRNA stability, antisense RNA-mediated interactions, or translation processes." (PMID 37762190, 2023). "MSX1 is expressed in regions of condensing ectomesenchyme in the tooth germ, and MSX1 gene polymorphisms have been associated with various forms of hypodontia in humans." (PMID 36672972, 2023). "Functional analysis of the Arg196Pro polymorphism in the MSX1 gene, involved in hypodontia, showed that the structurally defective protein with reduced thermal stability resulted in impaired DNA binding and protein interactions." (PMID 37762190, 2023). "Mutations in Msx1 have been linked to craniofacial defects and tooth agenesis in mice, while genetic alterations in human MSX1 are associated with cleft lip/palate and tooth agenesis." (PMID 35055037, 2022). "FOXC2 is also predicted to positively regulate LAMC2 and MSX1, a highly conserved transcription factor well-known to regulate tooth formation, and causing tooth agenesis in humans when mutated." (PMID 35217915, 2022). "Mutations in several genes have been associated with familial tooth agenesis, among others MSX1, PAX9, AXIN2, EDA, EDARADD, and EDAR." (PMID 33743023, 2021). "Result: the present work is intended to identify the involvement of MSX1 gene variants in familial hypodontia." (PMID 33708320, 2020). "A heterozygous mutation in either PAX9 or MSX1 has been widely reported to cause tooth agenesis in populations 6,11,13–16." (PMID 33014315, 2020). "Other research indicated that mutations in human MSX1 are associated with cleft palate and tooth agenesis." (PMID 32571211, 2020).
tooth agenesis (continued). "MSX1 homeodomain missense variants in subphenotypes of increasing severity of non-syndromic tooth agenesis (NSTA) and alterations in hydrogen bonds." (PMID 31914153, 2020). "In our current study, we described two novel variants of the MSX1 gene identified in two Chinese patients with isolated tooth agenesis: c.572T>C and c.590_594 dup TGTCC." (PMID 31914153, 2020). "In conclusion, the results of the present study showed that the variant genotype and variant T allele of the MSX1 rs8670 SNP increased the risk of hypodontia in the studied population." (PMID 31781599, 2019). "Mutations of MSX1 have been associated with non-syndromic cleft palate and tooth agenesis in humans, and Msx1-deficient mice exhibit severe craniofacial abnormalities, cleft palate, and absence of teeth." (PMID 31297068, 2019). "Based on our findings, we considered that the presence of the variant allele or variant genotype of the MSX1 rs8670 SNP increased the risk of hypodontia in the studied population." (PMID 31781599, 2019). "To further analyze how the novel mutation of MSX1 caused tooth agenesis, we constructed wild-type MSX1 expression vectors and performed site-directed mutagenesis to obtain the mutant MSX1 expression vector." (PMID 30134957, 2018). "For instance, genes whose mutations are associated with tooth agenesis, such as MSX1 and PAX9, also contain single nucleotide polymorphisms as genetic risk factors for orofacial clefts." (PMID 30305871, 2018). "Understanding these mechanisms will provide insights into novel therapeutic strategies for patients with tooth agenesis caused by MSX1 mutation in the future." (PMID 30134957, 2018). "We sequenced the coding regions of the PAX9 and MSX1 genes from nine patients with non-syndromic tooth agenesis, and identified a missense mutation, P20L, of PAX9 in a single familial case involving three patients in two generations." (PMID 29023497, 2017). "Transcription factors PAX9 and MSX1 play crucial roles in the development of permanent teeth at the bud stage, and their loss-of-function variants have been associated with congenital tooth agenesis." (PMID 29023497, 2017). "In conclusion, we identified a novel mutation in a familial case of non-syndromic tooth agenesis affecting the MH6 domain of MSX1." (PMID 27917906, 2016). "Several mutations, located mainly in the MSX1 homeodomain, have been identified in non-syndromic tooth agenesis predominantly affecting premolars and third molars." (PMID 27917906, 2016). "Several MSX1 mutations have been identified in tooth agenesis patients, and MSX1 is also a direct downstream target of WNT/β-catenin signalling during craniofacial development." (PMID 27857074, 2016). "Consistently, the dental mesenchyme-specific transcription factors (Msx1, Pax9, and Lhx6) were decreased in cultured mDMCs, and the mutation of these transcription factors was shown to cause tooth agenesis disorders." (PMID 26925321, 2016). "Here, we report a Japanese family with nonsyndromic tooth agenesis caused by a novel nucleotide substitution in the intronic region between exons 1 and 2 of the MSX1 gene." (PMID 26030286, 2015). "We here report a rare case of an intronic mutation of the MSX1 gene responsible for human tooth agenesis." (PMID 26030286, 2015). "To date, most MSX1 variants isolated from patients with tooth agenesis involve single amino acid substitutions in the highly conserved homeodomain or deletion mutants caused by frameshift or nonsense mutations." (PMID 26030286, 2015). "Further studies are needed to evaluate MSX1 variants related to tooth agenesis including a deficiency in the regulatory activity of histone H3 tri-methylation." (PMID 25101640, 2014). "We identified two novel MSX1 variants with an amino acid substitution within the homeodomain; Thr174Ile (T174I) from a sporadic hypodontia case and Leu205Arg (L205R) from a familial oligodontia case." (PMID 25101640, 2014).
tooth agenesis (continued). "The first case harboring a novel MSX1 variant was an apparent sporadic form of hypodontia in a 23-year-old female proband involving five missing teeth (plus the absence of an additional four third molars for a total of nine missing teeth)." (PMID 25101640, 2014). "In our current study, we describe two novel variants of the MSX1 gene identified in two Japanese patients with isolated tooth agenesis." (PMID 25101640, 2014). "For example, MSX1 is essential for tooth and facial bone development and its mutations lead to Witkop syndrome also known as nail dysplasia with hypodontia." (PMID 23342975, 2013). "At present, mutations causing non-syndromic tooth agenesis have been identified in MSX1, PAX9, AXIN2, EDA, and WNT10A." (PMID 23227268, 2012). "Given that impaired nuclear translocation of MSX1 is a known cause of tooth agenesis, we hypothesized that NKD1-mediated nuclear translocation of MSX1 might be a critical mechanism driving progenitor cell differentiation into odontoblasts." (PMID 41526338, 2026). "We further summarized the tooth agenesis pattern caused by MSX1 variants in non-syndromic tooth agenesis and drew a pattern diagram, which helps us further understand the etiology of tooth agenesis and provide help for clinical diagnosis and genetic counseling." (PMID 39767847, 2024). "Additionally, a review of 108 patients with known MSX1 variants was performed to identify patterns of tooth agenesis." (PMID 39767847, 2024). "Their findings showed for the first time that the MSX1 gene's novel cT671C mutation may be the etiological variant significantly involved in familial cases of hypodontia that only affect the second premolars and third molars." (PMID 38523193, 2024). "For example, in recent years, Dong Han identified five novel Msx1 heterozygous variants in multiple non-syndromic tooth agenesis in Chinese families, expanding the variant spectrum of isolated tooth agenesis and providing valuable information for genetic counseling." (PMID 38021739, 2023). "MSX1 of the Homeobox family is the first reported gene associated with tooth agenesis." (PMID 36561383, 2022). "Over 20 mutations in the MSX1 gene have been identified to cause isolated tooth agenesis." (PMID 36561383, 2022). "In the early results of some studies it was already suggested that MSX1 mutations, such as reading frameshift or missense mutations, may be associated with hypodontia." (PMID 33923458, 2021). "Several mutations in the homeodomain of MSX1 are associated to tooth agenesis or orofacial clefts." (PMID 33627176, 2021). "In addition to its nonsyndromic form, haploinsufficiency of MSX1 causes the syndromic form of tooth agenesis that includes cleft lip and/or palate." (PMID 34285200, 2021). "MSX1 belongs to Homeobox family and is the first gene reported in association with tooth agenesis." (PMID 33014315, 2020). "The missense variant (rs36059701) on MSX1 gene has been reported to play a role on orofacial clefts 29 and also the high prevalence (0.1036) suggests that this variant cannot be responsible for tooth agenesis in our studied population." (PMID 33014315, 2020). "Our results showed that the variant genotype (p=0.0008, OR = 2.9, 95% CI = 1.58–5.3) and variant T allele (p=0.0002, OR = 2.65, 95% CI = 1.6–4.39) of the MSX1 rs8670 SNP increased the risk of hypodontia in the studied population when the whole NSH group was compared with controls." (PMID 31781599, 2019). "These underlying mechanisms may provide insights into novel therapeutic strategies for patients with tooth agenesis caused by MSX1 mutation." (PMID 30134957, 2018). "Most MSX1 variants isolated from patients with tooth agenesis to date involved single amino acid substitutions in the highly conserved homeodomain/MH4 sequence; few frameshift, nonsense, and splice-site mutations that lead to premature termination have been examined." (PMID 27917906, 2016).